ADAM19 (ADAM metallopeptidase domain 19)
Diseases named in the same sentence as ADAM19 in open-access papers (continued):
Sharing a sentence is not in itself a finding about the gene and the disease.
metabolic syndrome (3 papers, 2017 to 2022). A cluster of metabolic risk factors for CARDIOVASCULAR DISEASES and TYPE 2 DIABETES MELLITUS. "Our exciting findings highlight that elevated ADAM19 protein expression is associated with the parameters of the metabolic syndrome in humans and mice." (PMID 28265178, 2017). "If Sp1, Sp3, NF-kappaB, and VDR are increased in obese and T2D subjects, then this could be a mechanism underlying the elevated expression of ADAM19 in the metabolic syndrome." (PMID 28265178, 2017). "In this study, we hypothesised that ADAM19 is associated with the metabolic syndrome in humans and mice." (PMID 28265178, 2017). "Recent studies have found that the elevated expression of ADAM19 is related to the occurrence of metabolic syndrome, and that it is expected to become a new target for treating metabolic syndrome in humans and mice." (PMID 35158649, 2022). "To determine the potential novel role of ADAM19 in the metabolic syndrome, we first conducted microarray studies on peripheral blood mononuclear cells from a well-characterised human cohort." (PMID 28265178, 2017). "We have found that high-level expression of ADAM19 in blood mononuclear cells from the SAFHS cohort correlated strongly with parameters of the metabolic syndrome and in particular BMI, relative fat, index of insulin resistance (HOMA-IR), and triglycerides." (PMID 28265178, 2017). "Future studies should aim to examine potential upstream regulators of the increase of ADAM19 protein expression in relation to the metabolic syndrome in humans and mice." (PMID 28265178, 2017). "Significantly, we show that, in humans, ADAM19 strongly correlates with parameters of the metabolic syndrome, particularly BMI, relative fat, HOMA-IR, and triglycerides." (PMID 28265178, 2017). "We are the first group to assess the effect of neutralising ADAM19 activity in vivo on the parameters of the metabolic syndrome." (PMID 28265178, 2017). "We found that high-level expression of ADAM19 in lymphocytes from the SAFHS cohort strongly correlated with the parameters of the metabolic syndrome." (PMID 28265178, 2017). "We sought to ascertain whether the human metalloproteinase A Disintegrin and Metalloproteinase 19 (ADAM19) correlates with parameters of the metabolic syndrome in humans and mice." (PMID 28265178, 2017). "Combined, this novel data provides evidence that neutralising antibody directed against the metalloproteinase domain of ADAM19 could be a potential therapeutic to alleviate symptoms of the metabolic syndrome." (PMID 28265178, 2017). "It would be insightful to ascertain whether furin protein levels are elevated in human patients with the metabolic syndrome and whether the binding of furin to ADAM19 pathogenically activates ADAM19 in vivo." (PMID 28265178, 2017). "This novel finding provides evidence that neutralising antibody directed against the metalloproteinase domain of ADAM19 could be a potential therapeutic to alleviate symptoms of the metabolic syndrome." (PMID 28265178, 2017). "We examined whether neutralising the metalloproteinase domain of ADAM19 would reduce the parameters of the metabolic syndrome in vivo." (PMID 28265178, 2017). "As TNF-α is a substrate for ADAM19, we hypothesise that the shedding of TNF-α by the ADAM19 metalloproteinase domain potentially exacerbates the pathogenesis of the metabolic syndrome." (PMID 28265178, 2017). "We showed for the first time in humans that both ADAM19 and ADAM28 are strongly correlated with parameters of the metabolic syndrome, particularly BMI, relative fat and the index of insulin resistance (HOMA-IR)." (PMID 33904577, 2021). "It is highly likely that ADAM17, ADAM19 and ADAM28 work in concert to promote the metabolic syndrome." (PMID 33904577, 2021). "Our group has previously sought to ascertain whether the metalloproteinases ADAM19 and ADAM28 correlate with parameters of the metabolic syndrome in mice and humans." (PMID 33904577, 2021).
metabolic syndrome (continued). "After considering our previous metabolic studies with regards to ADAM19 and ADAM28 and the fact that ADAM17 plays a multitude of roles in the pathogenesis of many diseases, it is vital to further understand the role ADAM17 plays in promoting features of the metabolic syndrome." (PMID 33904577, 2021).
non-small cell lung carcinoma (3 papers, 2020 to 2024). A group of at least three distinct histological types of lung cancer, including non-small cell squamous cell carcinoma, adenocarcinoma, and large cell carcinoma. "These regulatory networks encompassing circ_0048856-miR-1287-5p, circ-MEMO1-miR-101-3p-KRAS, and circ_00007355-miR-345-5p-ADAM19 play a role of detection of non-small cell lung cancer." (PMID 39021878, 2024). "For example, MiR-145 changes the sensitivity of non-small cell lung cancer to gefitinib through targeting ADAM19." (PMID 36077665, 2022).
ovarian carcinoma (3 papers, 2011 to 2019). A malignant neoplasm originating from the surface ovarian epithelium. "Moreover, dysregulation of transforming growth factor-β/SMAD4 signaling leads to epigenetic silencing of its downstream target ADAM19 in ovarian cancer cells." (PMID 29138461, 2017). "In addition, repression of ADAM19, a SMAD target gene, has been associated with the repressive histone modifications, H3K27me3 and H3K9me2, and histone deacetylase in ovarian cancer cells, while the promoter of ADAM19 was unmethylated." (PMID 21541038, 2011).
leiomyoma (2 papers, 2020 to 2023). A well-circumscribed benign smooth muscle neoplasm characterized by the presence of spindle cells with cigar-shaped nuclei, interlacing fascicles, and a whorled pattern. "We found that leiomyoma-associated fibroblasts could secrete ECM including collagen, fibronectin and ADAM19." (PMID 37215998, 2023).
Obesity (2 papers, 2017 to 2021). Accumulation of substantial excess body fat. "We also demonstrated in our diet-induced obesity mouse model that neutralising ADAM19 therapy results in weight loss and improves insulin sensitivity." (PMID 33904577, 2021). "Excitingly, we demonstrate in our diet induced obesity mouse model that neutralising ADAM19 therapy results in weight loss, improves insulin sensitivity, and reduces liver TNF-α levels." (PMID 28265178, 2017). "Interestingly, our group and others have shown that TNF-α is also a substrate for ADAM19 and therefore it is possible that ADAM19 may have an underlying role in the pathogenesis of obesity and T2D." (PMID 28265178, 2017). "We found that ADAM19 protein levels are increased in the highly steatotic livers of mice that have HFD-induced obesity and T2D compared to mice fed a normal chow." (PMID 28265178, 2017). "These significant and novel clinical observations provided strong support for a role of ADAM19 in the regulation of human obesity, insulin resistance, and T2D." (PMID 28265178, 2017). "Secondly, we examined the expression of ADAM19 in liver and gonadal white adipose tissue using an in vivo diet induced obesity mouse model." (PMID 28265178, 2017). "Whilst discussing potential regulators of ADAM19, it is relevant to also consider what transcriptionally controls ADAM19 expression in obesity and T2D." (PMID 28265178, 2017). "It would be intriguing to investigate the effect of TGF-β1 on ADAM19 expression and activation in our mouse model of obesity and T2D." (PMID 28265178, 2017). "The outcomes of this study provide novel insights into the ADAM19-mediated pathogenesis of obesity, insulin resistance, and T2D." (PMID 28265178, 2017). "We identified for the first time that neutralising the ADAM19 metalloproteinase domain reduced high fat diet induced obesity and improved insulin sensitivity in obese and T2D mice." (PMID 28265178, 2017). "These novel results provide evidence that neutralising antibody directed against the metalloproteinase domain of ADAM19 could be a potential therapy for anti-obesity agents." (PMID 28265178, 2017). "This novel data suggests that the ADAM19 metalloproteinase domain may play a crucial role in obesity, insulin resistance, and T2D." (PMID 28265178, 2017). "We are the first to show that neutralising ADAM19 activity reduces high fat diet induced obesity." (PMID 28265178, 2017). "Our study is the first to examine the role of ADAM19 in obesity, insulin resistance, and T2D." (PMID 28265178, 2017). "Our group is the first to examine the role of ADAM19 in obesity and T2D." (PMID 28265178, 2017). "Therefore, neutralisation of ADAM19 may be a potential therapeutic approach to treat obesity and T2D." (PMID 28265178, 2017). "Therefore, neutralisation of ADAM19 and ADAM28 may be a potential therapeutic approach to treat obesity and T2D." (PMID 33904577, 2021).
renal cell carcinoma (2 papers, 2015). "An overexpression of ADAM19 in endometrial carcinoma and its correlation with the progression and prognosis as well as in renal cell carcinomas has been reported." (PMID 26482227, 2015).
acute kidney injury (1 paper, 2025). Sudden and sustained deterioration of the kidney function characterized by decreased glomerular filtration rate, increased serum creatinine or oliguria. "Further significantly upregulated transcripts related to inflammatory processes included ADAM19, PD-L1 (CD274), non-canonical NF-kB genes NFKB2 and RELB, furthermore IFITM1, JAML -linked with acute kidney injury - IRX3-linked with metabolic inflammation - and PRDM1-observed in gouty arthritis." (PMID 40281125, 2025).
angiosarcoma (1 paper, 2024). A malignant tumor arising from the endothelial cells of the blood vessels. "• In rat and human angiosarcoma, miR-23 target genes (Ccnd1, Adam19, Plau, and Wsb1) that increase invasiveness and metastasis were enriched." (PMID 38826780, 2024).
Anxiety (1 paper, 2012). Intense feelings of nervousness, tension, or panic often arise in response to interpersonal stresses. "Our results showed a positive correlation between ADAM19 and psychosis (r = 0.595 p = 0.019); PS1 and mania (r = 0.535, p = 0.040); PS1 and depression (r = 0.567, p = 0.027) in BA9, and BACE1 with anxiety (r = 0.608, p = 0.03) in the hippocampus." (PMID 22590542, 2012).
benign prostate hyperplasia (1 paper, 2016). "Excitingly, we report for the first time that human prostate carcinoma samples have low ADAM19 expression when compared with benign prostate hyperplasia samples (BPH)." (PMID 26912236, 2016).
breast invasive carcinoma (1 paper, 2021). "ADAM19 belongs to the ADAM (a disintegrin and metalloproteinase) family that comprises transmembrane and secreted proteins and is found to be highly expressed in various human carcinomas including breast invasive carcinoma (BRCA)." (PMID 33548228, 2021).
chronic obstructive pulmonary disease (1 paper, 2015). A chronic and progressive lung disorder characterized by the loss of elasticity of the bronchial tree and the air sacs, destruction of the air sacs wall, thickening of the bronchial wall, and mucous accumulation in the bronchial tree. "Some researches from China showed that ADAM19 might have effects on testis development and chronic obstructive pulmonary disease." (PMID 25799050, 2015).
colorectal adenocarcinoma (1 paper, 2023). The most common type of colorectal carcinoma. "Similarly, we found that ADAM19 is significantly overexpressed in colorectal adenocarcinomas, corroborating a previous study comparing a small number (n=14) of colorectal tumors to normal tissue." (PMID 36890812, 2023).
colorectal tumor (1 paper, 2023). "Bioinformatic analyses showed that both KLF7 and ADAM19 are upregulated in colorectal tumors as well as associated with worse survival and their downregulation impaired HCT116 clonogenic activity." (PMID 36890812, 2023). "Antagonizing this axis may potentially suppress colorectal tumor formation, and likewise the inhibition of BHLHE40-regulated genes such as ADAM19 or KLF7 may have therapeutic value." (PMID 36890812, 2023).
congenital heart disease (1 paper, 2024). A heart disease that is present at birth. "Nevertheless, “mouse is not man;” for instance, the impressive effect of ADAM−/− on cardiac defects has not translated into documenting the effects of ADAM19 on human congenital heart disease." (PMID 38331475, 2024).
Crohn disease (1 paper, 2018). A gastrointestinal disorder characterized by chronic inflammation involving all layers of the intestinal wall, noncaseating granulomas affecting the intestinal wall and regional lymph nodes, and transmural fibrosis. "Fasting responsive genes were also regulated by variants associated to Crohn’s disease (PTGER4), Rheumatoid arthritis (PHLDB1), Lung Function (ADAM19) and with cardiac troponin (TNNT2)." (PMID 30193568, 2018).
Duane retraction syndrome (1 paper, 2020). Duane retraction syndrome (DRS) is a congenital form of strabismus characterized by horizontal eye movement limitation, globe retraction and palpebral fissure narrowing in attempted adduction. "For example, ADAM19 is known to participate in neuromuscular junction formation, while MAFB loss-of-function and dominant-negative mutations result in a congenital eye-movement disorder known as Duane retraction syndrome." (PMID 32380717, 2020).
exfoliation syndrome (1 paper, 2010). An autosomal dominant disorder caused by mutations in the LOXL1 gene, encoding lysyl oxidase homolog 1. "Using a proteomic approach, ADAM-19, −21, and ADAMTS-8 were detected in the anterior lens capsules of patients with co-existing Exfoliation syndrome (XFS)." (PMID 21197111, 2010).
fibrosis (1 paper, 2024). the formation of excess fibrous connective tissue in an organ or tissue in a reparative or reactive process. "ADAM19 exhibited a significant upregulation in skin tissues of SSc patients, as well as in wound healing and a HOCl-induced fibrosis mouse model." (PMID 39716051, 2024). "In this study, we investigated the expression levels of ADAM19 in the skin tissues of patients with SSc and a mouse model of hypochlorite (HOCl)-induced fibrosis." (PMID 39716051, 2024). "Immunohistochemistry revealed an elevated expression of ADAM19 in the fibroblasts of skin tissues from SSc patients and the HOCl-induced fibrosis mouse model compared to the control group." (PMID 39716051, 2024). "RT-PCR also demonstrated a substantial upregulation in the mRNA expression levels of ADAM19 and fibrosis-related genes (COL1A1, COL1A2, and FN1) in the skin tissues of the HOCl-induced fibrosis mouse model compared to controls." (PMID 39716051, 2024).
IgA nephropathy (1 paper, 2013). "The role of ADAM19 in progression of IgA nephropathy might be the regulation of the A2M downstream processes, such as binding to cytokines which result in inflammation, or regulation of complement and coagulation pathway by cleavage of this protein." (PMID 24339887, 2013).
Infertility (1 paper, 2022). "It has been suggested that MAP4K4 affects SH3PXD2A-binding enzymes ADAM12, ADAM15, and ADAM19, which has been shown to be associated with infertility in mutant mouse models." (PMID 36497065, 2022).
Insulin resistance (1 paper, 2017). Increased resistance towards insulin, that is, diminished effectiveness of insulin in reducing blood glucose levels. "Finally, we investigated the effect of neutralising ADAM19 on diet induced weight gain, insulin resistance in vivo, and liver TNF-α levels." (PMID 28265178, 2017). "Our novel data suggest that ADAM19 is pro-obesogenic and enhances insulin resistance." (PMID 28265178, 2017).
lung diseases (1 paper, 2024). "Adam19 increases extracellular matrix deposition in response to TGF beta, which is important in many lung diseases." (PMID 39153120, 2024). "Adam19 promotes the release of TNF, which affects lung function and contributes to lung diseases such as asthma, COPD, and lung fibrosis." (PMID 39153120, 2024).
melanoma (1 paper, 2019). A malignant, usually aggressive tumor composed of atypical, neoplastic melanocytes. "Taqman relative PCR of cloaked and uncloaked tumour ovarian cells revealed that ADAM19 is upregulated in platelet cloaked ovarian and melanoma cells compared with uncloaked cells." (PMID 30908480, 2019).
metastatic cancer (1 paper, 2017). A carcinoma which has spread from the original site of growth to another anatomic site. "These included genes which are implicated in inflammation and inflammatory responses to cancer (PTX3, IL8, TNFSF10, SERPINB13 and ANKRD1) and those involved in cell adhesion, cell migration and ECM degradation of importance in metastatic cancer (MMP12, MMP1 and ADAM19)." (PMID 28555042, 2017).
nephritis (1 paper, 2022). Inflammation of renal tissue. "An abnormally high expression of ADAM19 is also associated with nephritis and fibrosis, while the niche targeting inhibition of ADAM19 may be essential for the treatment of inflammatory diseases." (PMID 36534664, 2022).
osteoporosis (1 paper, 2023). A condition of reduced bone mass, with decreased cortical thickness and a decrease in the number and size of the trabeculae of cancellous bone (but normal chemical composition), resulting in increased fracture incidence. "Second, our negative results could not totally deny the potential of ADAM12, ADAM19, ADAM23 and ADAMTS6 as biomarkers for osteoporosis due to the weakness of MR analysis in identifying non-linear relationship." (PMID 37468870, 2023).
osteosarcoma (1 paper, 2024). A usually aggressive malignant bone-forming mesenchymal neoplasm, predominantly affecting adolescents and young adults. "To corroborate these findings in a more physiological cell model, we used human osteosarcoma U2OS cells in which we measured PTHR1-mediated cAMP accumulation with the fluorescence resonance energy transfer (FRET)-based cAMP biosensor Epac-S-H187, in the absence or presence of ADAM19." (PMID 38331475, 2024).